STAT1 (signal transducer and activator of transcription 1)
Diseases named in the same sentence as STAT1 in open-access papers (continued):
Sharing a sentence is not in itself a finding about the gene and the disease.
melanoma (continued). "In addition, the protective factors of skin melanoma, STAT1, IRF1, and FLI1, may modulate melanoma cell responses to NK or T cells." (PMID 37435067, 2023). "In addition, unphosphorylated or phosphorylated STAT1 and STAT3 are coordinately upregulated by both IFN-α and IFN-γ and may represent a marker for the dynamic mechanism of melanoma progression and host response." (PMID 37047709, 2023). "Importantly, we discovered that STAT1, IRF1, and FLI1, the protective factors of melanoma, may regulate the response of melanoma cells to NK and T cells by modulating the expression of positive NK and T cell regulation activation-related genes." (PMID 37435067, 2023). "However, our study clearly expands on this concept and is unique in that it examines the metabolic roles of Nampt induction directly by IFNγ-dependent Stat1 recruitment to NRE1 and the effects of this phenomenon in the context of the immune cells in the TME, including melanoma patients." (PMID 33976173, 2021). "In IL-2 therapy for melanoma, the absence of STAT1 was correlated with increasing clinical stage." (PMID 33511023, 2021). "YTHDF1 might negatively regulate STAT1 and further facilitated melanoma development, but the roles of STAT1 and CD86 in the general network were not large enough to mitigate the trend of disease development." (PMID 32549786, 2020). "Although putative binding sites for STAT1 on PD-L1 promoter have been postulated, active binding of STAT1 on PD-L1 gene promoter could not be demonstrated in melanoma cells." (PMID 29765155, 2018). "For instance, RNA-seq analysis of human melanoma COLO829 cells transfected with MITF short hairpin RNA (shRNA) demonstrates an up-regulation of over 17 of the same 55 innate immune DEGs identified in Mitfmi-vga9/+ McSCs, including Ifih1, Ifit3, Irf7, Parp9, and Stat1 (GSE50686)." (PMID 29723194, 2018). "However, a smaller study provided evidence that STAT1 expression in melanoma tissue does not correlate with patients’ response to adjuvant IFNα." (PMID 26735690, 2016). "To test potential interactions between FLLL32 or FLLL62 and STAT1 in a biologic system, we investigated the effects of pre-treatment with these inhibitors on IFN-γ-induced signaling and gene expression of representative metastatic human RCC and melanoma cell lines." (PMID 22899991, 2012). "Firstly, the concentration of the endogenous IFNγ may be too low to stimulate the IFNγR; secondly, IFNγR is functionally inactive, as demonstrated in renal cell carcinomas; and, finally, STAT-1 lacks TGCT, as shown in pul-monary carcinoma and malignant melanoma cells." (PMID 12942126, 2003). "Unlike in melanoma cells, these results suggest a reversible activation of central nervous-system-specific IFN/STAT1 signaling." (PMID 34771447, 2021). "Genetic alterations in antigen presentation (B2M, HLA-A) and IFNγ signaling (IFNGR, STAT1 and JAK1/2) in non-responding melanoma patients are uncommon, and not restricted to non-responding patients." (PMID 32312968, 2020). "Other cell lines with a negative correlation between VAV2 and STAT1 included the leukemias CCRFCEM and SR, the melanoma M14, the non-small cell lung cancers H226 and H460, and the prostatic adenocarcinoma PC3." (PMID 30653502, 2019). "However, in our study, we showed that inhibition of IFN-γ secretion itself could also contribute to abnormal STAT1 activation in melanoma patients, because STAT1 was not directly phosphorylated by IL-2 signaling, but depended on IFN-γ released by NK and T lymphocytes when stimulated with IL-2." (PMID 27153543, 2016). "Increased expression of immunosuppression-related genes, including IDO1, was detected after downregulation of WARS without a change in the phosphorylation status of STAT1, whereas a strong correlation between the levels of IFN-γ and IDO-1 was found in different types of melanoma." (PMID 40108693, 2025).
melanoma (continued). "However, comparable to the melanoma cells, HIF1α (or the HIF1-pathway gene-signature) did not significantly correlate with PD-L1 expression in TAMs, while STAT1 (or the JAK/STAT-pathway gene-signature) did." (PMID 34268602, 2022). "Notably, deletion of protein tyrosine phosphatase nonreceptor type 2 (PTPN2), a negative modulator of STAT1/JAK1 signaling, enhanced the efficiency of immunotherapy in melanoma tumors by increasing the activation of CD8+ T cells and the IFN-γ signaling pathway." (PMID 34827646, 2021). "By developing mechanisms to introduce STAT1 DNA into tumors lacking the protein and by treating the patient with a course of interferon, it may be possible to induce MHC I and MHC II expression on the cell surface of melanoma, leading to an increased response by the patient’s own immune system." (PMID 25690042, 2015).
COVID-19 (131 papers, 2020 to 2026). A disease caused by infection with severe acute respiratory syndrome coronavirus 2. "In hyperinflammatory syndromes like COVID-19, PTIC administration decreases the M1 subset, chemokines, and growth factors associated with STAT-1, improving the acute phase of the infection and avoiding long COVID-19." (PMID 39940787, 2025). "In severe COVID-19 patients, the hyperinflammatory response, also called the cytokine storm, is a hallmark feature with elevated circulating levels of IL-2/4/6/10, STAT1/2/3, and TNF-a." (PMID 38257800, 2024). "Other genes commonly associated with COVID-19 immune responses (e.g., Stat1, Myd88, Il1b Nlrp3, Cdkn1a, and Casp1) were also upregulated in responder brains." (PMID 36739463, 2023). "Corticosteroid treatment suppresses pathologic interferon responses in monocytes by downregulating STAT1 in patients with high-risk COVID-19." (PMID 36941461, 2023). "Several studies have indicated that phosphorylated STAT1 increases in severe COVID-19 patients, causing STAT1 signaling dysfunction and failed IFN activation." (PMID 35625619, 2022). "In contrast, the M protein-specific CD4+ TCLs had a transcriptomic signature of marked suppression of STAT1-IFRs-interferon pathway signaling, a signature that is virtually indistinguishable from the molecular signature seen associated with severe COVID-19." (PMID 35844575, 2022). "The dysregulated functionality of DCs in COVID-19 is associated with viral antagonism of the phosphorylation of signal transducer and activator of transcription 1 (STAT1), which is a key regulator of type I, II, and type III IFN signaling pathway." (PMID 33757410, 2021). "In COVID-19 cases caused by the SARS-CoV-2 N protein that inhibits the phosphorylation of STAT1 and STAT2, the conditions also suppress IFN signaling." (PMID 34209818, 2021). "A number of convergent findings suggest de-mono-ADP-ribosylation (de-MARylation) of STAT1 by the SARS-CoV-2 nsp3 as a putative cause of the cytokine storm observed in the most severe cases of COVID-19." (PMID 32549200, 2020). "The detectable anti-IFN-γ autoAbs may be associated with COVID-19 severity through their functional blockade effects on IFN-γ-mediated STAT1-phosphorylation." (PMID 36810114, 2023). "STAT1 is an inflammation-related transcriptional activator involved in infection and inflammatory diseases, including OA and coronavirus disease 2019." (PMID 37400752, 2023). "Both NF-κB and STAT1 signaling, as well as complement activity perse have been shown to enhance with cellular ageing in other contexts, which maypartially explain why the elderly are at greater risk of hyper-inflammation with COVID-19 thanthe young." (PMID 32702726, 2020). "Strongly neutralizing anti-IFN-α AAbs, with high titers (>20,000 ng/mL) and the ability to inhibit STAT1 phosphorylation, were identified in three severe COVID-19 cases." (PMID 40733719, 2025). "COVID-19 patients under PTIC treatment showed a significant decrease in Mo1 percentages and cytokines (IP-10/MIF/eotaxin/IL-8/IL-1RA/M-CSF) associated with STAT1 and an increase in the Mo2 subset." (PMID 39940787, 2025). "They observed that in COVID-19 patients, three signaling pathways were activated: the apoptosis pathway, the signal transducer and activator of the transcription 1 (STAT1) pathway, and the interferon regulatory factor 3 (IRF3) pathway." (PMID 38542251, 2024). "COVID-19 induces a shift from STAT1 to STAT3 signaling, enhancing pro-inflammatory responses and cytokine storms." (PMID 39156288, 2024). "STAT1 is known to be involved in immune responses and antiviral activity and is reported to be upregulated in mild and severe COVID-19 cases, with the phosphorylation of the gene highly enhanced in severe disease states." (PMID 39040605, 2024).
COVID-19 (continued). "By use of ingenuity pathway analysis (IPA) and publicly available ChIP-Seq of STAT1, interferon (INF)-JAK1/2-induced STAT1 signaling pathway is predicted to induce complement C3 expression and its activation in COVID-19 infected human lung epithelial cells." (PMID 38538870, 2024). "When phosphorylation of STAT1 was assessed using plasma from healthy subjects and COVID-19 patients, the levels were comparable between the two groups." (PMID 38647550, 2024). "Auto-abs to type I IFN in the plasma from COVID-19 patients suppressed IFN-α2-induced STAT1 activation, suggesting the possible neutralizing activity of these auto-abs to type I IFN." (PMID 38647550, 2024). "The Protein-Protein Interaction analysis identified DDX58, MX1, and STAT1 as central genes in the context of COVID-19 and TB." (PMID 39639868, 2024). "STAT1 transcriptional up-regulation in severe COVID-19 patients is a potential predictive biomarker and target for certain interferon pathway-targeted therapies." (PMID 37340462, 2023). "Interferon signaling induces the IFN-stimulated gene (ISG) expression by phosphorylating STAT1, and STAT1 phosphorylation was found to increase in severe COVID-19 cases, indicating an imbalanced JAK/STAT signaling and lack of ISG-induced transcription." (PMID 36851647, 2023). "In humans, a single-cell transcriptional study performed in PBMCs from patients with COVID-19 suggested that the IFNα and IFNγ function in T cells and dendritic cells promote disease severity by activating STAT1." (PMID 37893073, 2023). "A previous study found that seriously affected COVID-19 patients had an increased level of STAT1 and IRF9." (PMID 37053191, 2023). "The identified TFs, such as FOXC1, GATA2, YY1, FOXL1, FOXO3, STAT1 and STAT3, are associated with COVID-19." (PMID 37261353, 2023). "That is, first, ORF6 inhibits the nuclear translocation of one of the key signaling molecules for COVID-19, STAT1, through its direct binding to antagonize the IFN signaling." (PMID 35590097, 2022). "In contrast, STAT1 phosphorylation was increased in severe COVID-19 cases, pointing to an imbalanced JAK/STAT signaling and lack of ISG induced transcription." (PMID 35663932, 2022). "COVID-19 patients with severe symptoms showed a lower expression pattern of STAT-1 compared to the healthy group at mRNA (p = 0.0002) and protein (p = 0.0002) status." (PMID 35842705, 2022). "They observed that both Siglec-1 (a well described downstream molecule in interferon signaling) and STAT1 levels in plasmablasts and monocytes were higher in patients mildly affected by COVID-19 than in those with severe infection." (PMID 35456913, 2022). "The dysregulation of all three types of interferons (I, II, III) in COVID-19 patients reveals the effect of infection on the common genes of these cytokines (such as STAT1, STAT2)." (PMID 36405703, 2022). "For example, IFN gamma receptor was among the top CSSG genes in monocytes and dendritic cells, while STAT1 was sensitive to COVID-19 and xenobiotics in monocytes, NK cells, and T-cells." (PMID 34830356, 2021). "Both M protein and anti-CD3 Ab induced CD3ζ (Tyr83), ZAP70 (Tyr319), and STAT1 (Ser727) phosphorylation in COVID-19 CD4+ T cells." (PMID 34878838, 2021). "We found that the IFN-II signaling pathway has changed significantly in the patients of COVID-19 and can activate the master regulator STAT1 to regulate the downstream ACE2 expression in the secretory cells." (PMID 34858473, 2021). "We also found that using a depth of three in both IL-6 receptor–hydroxychloroquine and STAT1–chloroquine cases resulted in more information related to COVID-19." (PMID 34209818, 2021). "As well as the macrophage-related genes MYD88 and STAT1, were upregulated in bronchoalveolar cells from patients with mild COVID-19, while cells from patients with severe COVID-19 were characterized by upregulation of the CD163 marker of M2 macrophages." (PMID 34225749, 2021).
COVID-19 (continued). "PTIC could be relevant for treating STAT1-mediated inflammatory diseases, including COVID-19 and long COVID-19." (PMID 39940787, 2025). "PTIC could be relevant for treating STAT1-mediated inflammatory diseases, including COVID-19 and long COVID." (PMID 39940787, 2025). "This study’s strengths are highlighted by the potential role of LAIR1 engagement by PTIC in leading in vitro M1 to M2 polarization through the downregulation of STAT1 phosphorylation and the replication of the effect in mild to moderate COVID-19 patients under treatment with PTIC." (PMID 39940787, 2025). "In mice immunized through the administration of recombinant SARS-CoV-2 spike protein antigens, the decline in anti-COVID-19 antibodies caused by OxS and SOD decreased upon virus re-exposure, and the activation of the JAK2/STAT1 pathway was efficiently counteracted by upregulating SOD production." (PMID 39768279, 2024). "We observed that COVID-derived PBMCs and monocytes showed significantly increased levels of receptor subunit Gp130, the receptor-associated kinase JAK2, STAT1, and STAT3, and the negative regulator SOCS3 (respectively) as a function of COVID-19 disease severity." (PMID 37310504, 2023). "To validate that anti-IFN-γ autoAbs are a cause and not a consequence of severe/critical COVID-19, we performed a flow cytometry analysis and revealed a neutralizing capacity of these auto-Abs through blocking STAT1 phosphorylation." (PMID 36810114, 2023). "NSP1 and ORF6 from SARS-CoV-2 may impair STAT1 function in COVID-19 patients, resulting in compensatory STAT3 hyperactivation." (PMID 36059536, 2022). "Additionally, JAK inhibitors also reduce STAT1 activity, therefore their usage in patients with COVID-19 must be done with caution." (PMID 36111104, 2022). "An upregulation of STAT1 has also been reported in mildly to severely affected COVID-19 patients." (PMID 36553678, 2022). "With the potential use for COVID-19 treatment of existing drugs that enhance STAT1 or inhibit STAT3 functions, problems could arise." (PMID 35663932, 2022). "Moreover, a comparative study of COVID-19 and influenza showed the activation of STAT3/NF-κB in PBMCs of patients infected with influenza A virus (IAV)- vs. the activation of STAT1/IRF3 in COVID-19 patients." (PMID 34394120, 2021). "Epigenes that participate in the immune response through different mechanisms (response to interferon or NF-kB complex) are among the main genes identified and are evident drug target candidates for COVID-19 because they already have associated drugs targeting them (such as STAT5A and STAT1)." (PMID 34031419, 2021). "All the target connections are based on the reported experimental evidence, showing that transcriptional factor STAT1 may play a central role in the 14-gene network for COVID-19 diagnosis." (PMID 34880855, 2021). "IL-6 receptor and STAT1 are both related to immune systems and COVID-19." (PMID 34209818, 2021). "In mild cases of COVID-19, we further observed that the expression of PSMB8 in alveolar monocytes/macrophages was correlated with that of genes associated with the polarization of M1 macrophages, such as CD68, MYD88, and STAT1." (PMID 34225749, 2021). "Additionally, we showed that mRNA levels of both T-bet and STAT-1 transcription factors, as key regulators of type 1 immune response, were also significantly reduced in COVID-19 patients." (PMID 33692788, 2021). "Therefore, in the STAT1-chloroquine case, there are more irrelevant nodes and information to COVID-19 extracted from top-ranked paths." (PMID 34209818, 2021). "In our STAT1-GOF patients, we can hypothesize thatthe concomitant treatment with a reduced dose of JAKinib during SARS-CoV2 infection might have balanced the risk of hyperinflammatory complications after COVID-19." (PMID 38578354, 2024). "Additionally, it has also been suggested that enhancing STAT1’s activity might be an effective COVID-19 treatment, thus bypassing the adverse effects of IFN-based therapeutics." (PMID 36298734, 2022).